EML2 (EMAP like 2)
Description:
Tubulin binding protein that inhibits microtubule nucleation and growth, resulting in shorter microtubules.
Synonyms: EMAP-2; EMAP2; ELP70
Tractability: PROTAC: ubiquitination databases record sites on it; its protein half-life has been measured.
Gene: Protein-coding gene on chromosome 19 (45,606,994 to 45,645,602, reverse strand). Ensembl gene ENSG00000125746.
Subcellular location: Cytoplasm, cytoskeleton; Cytoplasm, cytoskeleton, spindle
Gene Ontology:
Molecular function: microtubule binding; protein binding; tubulin binding
Biological process: negative regulation of microtubule polymerization; regulation of microtubule nucleation; microtubule cytoskeleton organization; sensory perception of sound; visual perception
Cellular component: mitotic spindle; microtubule associated complex; cytoskeleton; spindle
Genetic constraint (gnomAD): Loss-of-function variants: 59 observed, 86.76 expected, observed/expected ratio (o/e) 0.68, 90% interval 0.55 to 0.85. The upper end of that interval is the gene's LOEUF score, 0.85, which puts it in group 3 of 6, group 1 being the genes least tolerant of losing a copy. Missense variants: 818 observed, 881.64 expected, observed/expected ratio (o/e) 0.93, 90% interval 0.88 to 0.98. Synonymous variants: 352 observed, 356.78 expected, observed/expected ratio (o/e) 0.99, 90% interval 0.9 to 1.08.
Homologues: Orthologues: chimpanzee EML2 (99% identical), dog EML2 (97% identical), pig EML2 (96% identical), mouse Eml2 (94% identical), rat Eml2 (94% identical), zebrafish eml2 (71% identical), tropical clawed frog eml1 (64% identical), guinea pig EML2 (63% identical), rabbit EML2 (62% identical). Paralogues in human: EML1 (68% identical), EML4 (57% identical), EML3 (53% identical), EML5 (37% identical), EML6 (36% identical), WDR90 (27% identical), CFAP44 (22% identical), CFAP251 (19% identical), CFAP52 (16% identical).
Diseases named in the same sentence as EML2 in open-access papers:
EML2 is named in the same sentence as 6 diseases in open-access papers, as found by Europe PMC text mining. Sharing a sentence is not in itself a finding about the gene and the disease. The quoted sentences say what the papers report.
cervical cancer (1 paper, 2025). A primary or metastatic malignant neoplasm involving the cervix. "In contrast, earlier studies in HeLa cervical cancer cells suggest that EML2 short variant (ELP70) binds tubulin in vitro via its HELP motif, inhibiting seeded nucleation and increasing microtubule catastrophes by weakening lateral interactions between protofilaments." (PMID 40398603, 2025).
mental retardation (1 paper, 2020). "The overexpression of DOPEY2 may contribute to mental retardation, while EML2 has a role in visual perception." (PMID 33228685, 2020).
type 2 diabetes (1 paper, 2017). "In addition to neurological activities, novel bimodal NORED regions that have potential roles in type 2 diabetes at the Gipr/Eml2 locus." (PMID 29387450, 2017).
tumor (1 paper, 2023). "PAPPA differs from BCL7C and EML2; its overexpression promotes tumor growth, and it is related to IGFBP hydrolysis and activation of NF-κB, PI3K, and other pathways, which are closely related to hair follicles and wool fibers." (PMID 37894908, 2023). "Both BCL7C and EML2 have similar functions as tumor suppressors, and both are related to islet β cells." (PMID 37894908, 2023). "EML2 plays an important role in mitosis, mainly in forming the spindle and interphase microtubule network, and often appears in cancerous tumor-related research as a tumor suppressor." (PMID 37894908, 2023).
EML2 also shares sentences with these, for which no sentence is quoted: Parkinson disease (1 paper); pituitary adenoma (1).